FTO (FTO alpha-ketoglutarate dependent dioxygenase)
Diseases named in the same sentence as FTO in open-access papers (continued):
Sharing a sentence is not in itself a finding about the gene and the disease.
Obesity (continued). "The observed correlation between obesity and LTL might also be explained by the fat mass and obesity associated (FTO) gene-involved pathways, as is shown in the review." (PMID 34393992, 2021). "Regarding the association between obesity-related genes and 25-OH-vitamin D, a recent study reported that 25-OH-vitamin D levels influence the effect size of FTO rs9939609 genotype on Roux-en-Y Gastric Bypass (RYGB) surgery-induced weight loss in obese patients." (PMID 34399781, 2021). "Future studies with larger sample sizes and including both sexes are needed to confirm the findings of this study on the relationship between serum levels of 25-OH-vitamin D with the expression of genes associated with obesity and the effect of FTO polymorphisms on this association." (PMID 34399781, 2021). "Also, our results of an FTO risk allele effect on total IS in males with severe obesity, should be of clinical interest." (PMID 33684170, 2021). "Exceptionally, fat mass- and obesity-associated (FTO) genes have been shown to be associated with obesity and TL, and the FOXO3 G allele of SNP rs2802292 significantly protected against aged-related TL loss relative to that of carriers of the common TT genotype." (PMID 33507936, 2021). "FTO, originally known as an obesity-susceptibility gene, is strongly associated with obesity risk." (PMID 34124065, 2021). "Understanding the interaction between diet and FTO variants in Indonesia may provide valuable insights for obesity management since Indonesian cuisine is naturally fatty, owing to the generous use of coconut milk and palm oil." (PMID 34743743, 2021). "Indeed, a polymorphism of the FTO gene, which has been shown to be consistently associated with obesity and body mass regulation in Europeans53–56, was also found to be positively associated with atypical depression." (PMID 33542229, 2021). "After correction for multiple testing, these authors identified 1649 CpG sites and 853 genes, including TCF7L2, fat mass and obesity-associated (FTO) and potassium voltage-gated channel subfamily Q member 1 (KCNQ1), with differential DNA methylation in T2D islets." (PMID 34769081, 2021). "This comorbidity between H. pylori infection and obesity may be caused by the pleiotropic effects of FTO and other genes." (PMID 34521966, 2021). "We also investigated the association of FTO (rs8050136) with obesity." (PMID 34442333, 2021). "Based on the fact that the FTO rs9939609 variants have shown an association with obesity in various ethnicity and obesity is a risk factor for CRC aetiology, the objective of this study was to investigate the genetic association of FTO rs9939609 variants with the risk of developing CRC in Iranians." (PMID 34650918, 2021). "At the fat-mass and obesity-associated gene (FTO) rs9939609 single nucleotide polymorphism (SNP), carriers of the obesity-risk A-allele present a higher risk of obesity compared to homozygous carriers of the T-allele in Europeans, primarily because of elevations in appetite and energy intake." (PMID 33348678, 2020). "Physical exercise and activity status may modify the effect of the fat mass- and obesity-associated (FTO) genotype on body weight and obesity risk." (PMID 32821265, 2020). "Presence of the FTO obesity-risk allele suppressed the expression of mitochondrial and thermogenesis genes with a striking resemblance between affected pathways and those appearing in ProFAT and BATLAS, underlining the importance of metabolic and mitochondrial pathways in thermogenesis." (PMID 32316277, 2020). "We hypothesize that FTO gene variants play a role in elevating BMI and obesity risk in the Balinese." (PMID 31915589, 2020). "On the other hand, the association of FTO polymorphisms with obesity may be influenced by dietary intake." (PMID 32843047, 2020). "FTO was initially identified as an obesity‐related gene by genome‐wide association studies." (PMID 33029866, 2020).
Obesity (continued). "The classic BMI-related FTO SNPs were rs9939609 (T/A), and compared with those who did not carry the risk allele, 16% of adults who carried the homozygous risk allele gained nearly 3 kg in weight, and the risk of obesity increased by 1.67 times." (PMID 33304380, 2020). "The FTO gene is one of the first loci identified for obesity risk by GWAS." (PMID 32899047, 2020). "This study suggests that in addition to nutritional regulation, FTO is also regulated by exercise and may be involved in exercise’s role in reducing obesity risk." (PMID 32821265, 2020). "This interaction may be explained by the observation that FOXA1 binds to four distinct intronic regions of the FTO (fat mass and obesity associated) gene, which has a known predisposing role to obesity." (PMID 32207560, 2020). "Sex has shown to influence the effect of the FTO polymorphism on obesity related traits." (PMID 32821265, 2020). "It is possible that estrogen could induce the expression of FTO (the fat mass and obesity-associated gene), in a manner that is depending on ESR1 (ESRα), promoting the proliferation of endometrial cancer cells." (PMID 33232273, 2020). "Then it was discovered that the dynamic demethylation process could be achieved by “erasers” including AlkB homolog 5 (ALKBH5), and fat mass and obesity-associated protein (FTO)." (PMID 32733807, 2020). "However, the influence ofFTO variants has been controversial among different populations.Moreover, there are only few studies associating FTO variants andextreme obesity, since sample selection is difficult and requires considerableeffort." (PMID 32154826, 2020). "Moreover, some genotypes of the FTO gene (a gene associated with fat mass and obesity) have been associated with risk of both obesity and depression." (PMID 32079538, 2020). "It is possible that increased expression of FTO may contribute to the higher risk of individuals with overweight or obesity in developing cancers." (PMID 32299393, 2020). "Besides the associationwith obesity, FTO variants have also been correlated to bodycomposition and obesity-related traits (Scuteriet al., 2007; Shabana and Hasnain, 2015)." (PMID 32154826, 2020). "Genetic studies of depleting either m6A methyltransferases, such as METTL3 and METTL14 or demethylase FTO (fat mass and obesity associated protein), have demonstrated their important roles in controlling cortical development and regulating brain cognitive functions." (PMID 32992647, 2020). "Fat mass and obesity-associated gene (FTO) is the most studied obesity-related gene up to date." (PMID 32398148, 2020). "Currently, the fat mass and obesity-associated (FTO) gene is the strongest risk loci for obesity." (PMID 32397403, 2020). "The fat mass and obesity-associated (FTO) gene is located on chromosome 16q12.2." (PMID 33817272, 2020). "Variants in the FTO gene associate with obesity and overweight phenotypes." (PMID 31888951, 2020). "Besides, it is widely acknowledged that the FTO (fat-mass and obesity-associated gene) is related to BMI and obesity." (PMID 32390949, 2020). "Furthermore, the risk allele at the FTO variant rs1421085 associates with increased BMI, obesity, and a number of other traits including T2D15." (PMID 33239696, 2020). "However, more convincing and systematic research studies are needed to decipher the causal mechanism between FTO non-coding variants and obesity or cancer." (PMID 33304380, 2020). "In addition, it is necessary to investigate other genes (isolated or associated) which have been demonstrated to be involved in obesity such as FTO, Melanocortin 4 Receptor - MC4R, Adenovirus 36 and beta 2 adrenoceptor-ADRB2." (PMID 32457643, 2020). "Hierarchical cluster analyses based on Pearson correlation showed that 91% of the FTO T/T donor samples clustered together and 83% of the FTO C/C obesity-risk donor samples appeared in the same main cluster and they were closer to the preadipocytes, considering ProFAT genes." (PMID 32316277, 2020).
Obesity (continued). "Numerous studies have identified the various fat mass and obesity-associated (FTO) genetic variants associated with obesity and its metabolic consequences; however, the impact of dietary factors on these associations remains unclear." (PMID 33114268, 2020). "In order to investigate the strong association of the obesity-associated (FTO) gene variants and obesity with epigenetic changes, a genome-wide methylation scan in obese and normal weight females identified 20 DM sites in obese females, of which one was hypomethylated site in NBPF3 gene." (PMID 32605309, 2020). "The present study provides a potential mechanism by which exercise may attenuate the influence of the FTO rs9939609 polymorphism on obesity risk." (PMID 32821265, 2020). "The FTO gene is obesity-associated and has been replicated by many studies." (PMID 32457790, 2020). "In the early GWA study and subsequent validated studies, the authors suggested that FTO rs1121980 may represent a susceptibility locus for obesity risk." (PMID 32390949, 2020). "Moreover, the two strongest associations in the GWAS were from SNPs in FTO (rs1558902/ rs1421085, p = 1.67x10-7/1.75x10-7), highlighting the overall importance of this gene in relation to obesity." (PMID 31888951, 2020). "In humans, some FTO SNPs are strongly associated with a predisposition to obesity." (PMID 32747736, 2020). "Note that all the mutations in the FTO gene increase the odds of obesity risk." (PMID 31888951, 2020). "Fat mass and obesity-associated (FTO) gene is a candidate gene of obesity." (PMID 32193455, 2020). "At the same time, the effect of FTO on risk of obesity is attenuated by PA." (PMID 32835373, 2020). "Dietary macronutrients may indirectly affect body weight through their interactions with the fat mass and obesity associated (FTO) gene." (PMID 32843047, 2020). "The influence of FTO variants on the risk of obesity is consistentin Caucasian studies." (PMID 32154826, 2020). "So, it is plausible that FTO gene polymorphisms could change appetite and food intake that may lead to weight gain and obesity." (PMID 32843047, 2020). "The haplotype and the combinedeffects of FTO risk alleles on obesity susceptibility wereevaluated." (PMID 32154826, 2020). "FTO is also associated with obesity, food intake, and energy metabolism." (PMID 32411802, 2020). "Associations between FTO and obesity were just under genome-wide significance levels." (PMID 31888951, 2020). "FTO gene polymorphisms are associated with obesity and food intake." (PMID 31996075, 2020). "Regarding FTO rs9939609 genotype, about half of the subjects were AT (n = 98), 30% of them were TT (n = 60) and about 20% of them were homozygote for the known risk allele of obesity (n = 38)." (PMID 31996075, 2020). "As the name implies, FTO is intimately associated with obesity." (PMID 33292526, 2020). "FTO rs9939609 polymorphism is associated with the increased risk of obesity." (PMID 32843047, 2020). "FTO variants are also discussed as potential predictors of obesity treatment." (PMID 32578971, 2020). "Detecting FTO risk genotype carriers and modifying dietary intake according to the genetic profile may be a novel, efficient strategy to prevent obesity development." (PMID 33114268, 2020). "Therefore, our results suggest that FTO rs9939609and rs17817449 are risk factors for obesity; however, more functional studies arerequired to confirm these results." (PMID 32154826, 2020). "Also, they claimed that FTO can raise the susceptibility to obesity and overweight by inhibiting white adipose tissue browning." (PMID 32398148, 2020). "Until recently, the role of the FTO protein was practically unknown, even though FTO SNPs have been described as strong genetic factors linked to predisposition to obesity and the development of T2D." (PMID 32747736, 2020). "For many years, FTO was thought to be of special interest due to its association with obesity." (PMID 32375858, 2020).
Obesity (continued). "People with a high body mass index may commonly carry FTO risk alleles and there are some SNPs of FTO positively associated with obesity." (PMID 32110378, 2020). "Generally, the FTO gene is associated with type 2 diabetes mellitus and obesity." (PMID 32133054, 2019). "The Fat mass and obesity-associated gene (FTO) is an established obesity-susceptibility locus; however, it remains unknown whether it influences vitamin B12 status." (PMID 31516636, 2019). "The ultimate goal of the work was to elucidate and underscore rapid population-specific fixation of the obesity associated genetic variant (haplotype) in European populations based on FTO intron 1 expanded haplotype frequency profiling in the major continental supergroups of the1000 Genome Project." (PMID 30871540, 2019). "In addition, an interesting relationship between variants in FTO and obesity has been suggested emphasizing the role of FTO in central regulation of several metabolic processes." (PMID 31728912, 2019). "Most notable genetic variants from FTO associated with obesity traits are a cluster of as many as 20 common SNPs from its first intron — particularly notable are rs1421085 (the study variant), rs9939609, rs1121980, rs8050136, rs3751812, rs17817449, and rs8050135." (PMID 32076432, 2019). "Indeed, the recent work on Polish population FTO haplotype analysis confirmed the obesity association with FTO intron 1 locus, but statistical significance held in males only." (PMID 30871540, 2019). "In addition to MC4R, loci in the FTO gene have been consistently linked with the risk of obesity with FTO being highly expressed in the hypothalamus and playing a role in the ghrelin, leptin, and melanocortin pathways." (PMID 30764585, 2019). "We used FTO gene variants as instruments to establish the relationship between obesity and B12 status and tested whether this relationship was modified by lifestyle factors." (PMID 31516636, 2019). "Therefore, the mechanisms underlying the contribution of FTO to the risk of obesity are apparently more complex than expected." (PMID 31852448, 2019). "Reports from another study indicated that RPGRIP1L may be partly or exclusively responsible for the obesity susceptibility signal at the FTO locus." (PMID 31075924, 2019). "Recently, a cross-sectional study in an Indian population showed that physical activity and dietary intake may modify the association between the FTO gene variants and obesity-related traits." (PMID 31516636, 2019). "Association studies have implicated single nucleotide polymorphisms (SNPs), particularly rs1421085, from the fat mass and obesity-associated (FTO) gene with body composition phenotypes, obesity, dietary intake, and physical activity in European, East Asian, and African populations." (PMID 32076432, 2019). "Thus, it would seem plausible that dietary habits can modify the FTO gene risk allele influence on obesity." (PMID 31477138, 2019). "Interestingly, there are some studies that have determined the relationship between FTO rs9939609 polymorphism and obesity based on BMI in females only." (PMID 31810473, 2019). "Metabolic inflexibility has been linked to the development of obesity and T2D and could provide another mechanism by which FTO is associated with increased susceptibility to becoming overweight and obese." (PMID 31635368, 2019). "Variants of the FTO gene are known to be the strongest genetic predictor of obesity to date." (PMID 31516636, 2019). "Initial reports suggested multiple single nucleotide polymorphisms (SNPs) within the first intron of FTO found on chromosome 16 were significantly associated with obesity in humans, although the association between FTO SNPs and FTO expression has been controversial." (PMID 31482095, 2019).
Obesity (continued). "Whether the FTO genotypes influence the association between obesity and vitamin B12 concentrations by modulating the gut microbiota composition and inducing metabolic inflammation requires further investigation utilizing fecal samples." (PMID 31516636, 2019). "Moreover, SNPs (single-nucleotide polymorphisms) within intron 1 of the FTO gene are linked with increased FTO expression, increased body weight, obesity, and type 2 diabetes." (PMID 31772698, 2019). "However, the current genetic models to predict obesity based on SNP associated with BMI loci deal with AUCROC between 0.546 (when FTO is the only gene considered) up to 0.575 (when considering 12 or 32 loci)." (PMID 30704070, 2019). "FTO is known to have a strong association with human obesity." (PMID 30999842, 2019). "•Carrying one FTO risk allele was linked to more physical activity which may moderate the FTO related obesity risk." (PMID 32550549, 2019). "Heterozygous carriers of one FTO risk allele showed greater physical activity before and after weight loss which might protect them in part from the higher obesity risk associated with FTO." (PMID 32550549, 2019). "Several GWAS studies have shown that variations in the FTO gene are associated with obesity." (PMID 31810473, 2019). "FTO is one of the genes known as a post‐GWAS gene, being mainly associated with obesity." (PMID 31033179, 2019). "The rs9939609 polymorphism of the fat mass and obesity-associated (FTO) gene has been associated with obesity, and studies have also shown that environmental/lifestyle interaction such as dietary intake might mediate this effect." (PMID 31635368, 2019). "The fat mass and obesity associated gene, FTO, is also associated with osteoporosis phenotypes." (PMID 31998240, 2019). "FTO-knockout mice showed protection from obesity but caused growth failure." (PMID 30922314, 2019). "Therefore, in this study we were interested in assessing the relationship between the common FTO gene polymorphism (rs9939609) with obesity, MS risk and disability in a cohort of MS patients." (PMID 31836807, 2019). "The fat mass and obesity-associated (FTO) gene is a well-established obesity-susceptibility locus." (PMID 32076432, 2019). "The related genes expression was reduced, which could be associated with m6A demethylase fat mass and obesity-associated (FTO)." (PMID 31615033, 2019). "A smaller share is attributed to genetic factors, which include the polymorphism of following genes: fat mass and obesity-associated gene (FTO), commonly referred to as the “obesity gene”, and gene coding for peroxisome proliferator-activated receptor gamma (PPARγ), resistin, and adiponectin." (PMID 31737129, 2019). "The present work aims to determine whether FTO genetic variants are associated with bipolar disorder and obesity, and to perform an in silico prediction of variant‐dependent functional impact on the developing brain transcriptome." (PMID 31033179, 2019). "FTO polymorphisms are associated with elevated body mass index and increased risk for obesity." (PMID 31998240, 2019). "Association between fat-mass-and-obesity-associated (FTO) gene and hip fracture susceptibility." (PMID 31998240, 2019). "Moreover, our association with obesity is consistent with previous reports, whereas the association with disability is novel and warrants further investigation on the role of FTO in disease progression." (PMID 31836807, 2019). "The association of the FTO gene with obesity was first identified in the Caucasian population, and the FTO gene’s SNPs have been shown to be associated with obesity-related parameters such as leptin levels, subcutaneous fat, fat mass, and waist and hip circumference." (PMID 31810473, 2019). "The FTO allele associated with obesity was significantly higher on two measures of body fat." (PMID 30124167, 2018).